PAX5 (paired box 5)
Diseases named in the same sentence as PAX5 in open-access papers (continued):
Sharing a sentence is not in itself a finding about the gene and the disease.
diffuse large B-cell lymphoma (23 papers, 2016 to 2025). "PAX5, the gene encoding paired box 5, is specifically upregulated in many cancers, including diffuse large B-cell lymphoma, breast cancer, glioblastoma, and pancreatic cancer." (PMID 38926764, 2024). "Histomorphology and immunohistochemistry showed a diffuse large B-cell lymphoma that was immunopositive for PAX5 and CD20, and immunonegative for CD3." (PMID 40119492, 2025). "Due to the abnormal expression of certain B-cell antigens (such as PAX-5+, CD79a+) by the tumor cells, the initial pathological report incorrectly diagnosed the lesion as “diffuse large B-cell lymphoma”." (PMID 41561755, 2025). "While previous studies have shown the disruption of various cancer-associated mutations, our focus on targeting oncogenes such as PAX5, MYC, and CD79B in diffuse large B-cell lymphoma (DLBCL) represents a significant advancement." (PMID 39469218, 2024). "Although PAX8 was immunoreactive and thus worrisome for anaplastic thyroid carcinoma, the tumor was eventually proven to represent PAX5 positive diffuse large B-cell lymphoma expressing cross-reactivity with polyclonal PAX8 antibody." (PMID 28078156, 2016). "Positive staining for p63 initially raised suspicion for poorly differentiated urothelial carcinoma; however, lack of staining for pancytokeratin and positive staining for LCA, CD20, CD79a, and PAX-5 confirmed the diagnosis of diffuse large B cell lymphoma." (PMID 27648316, 2016). "In addition, c-MYC, PAX5, and BCL-6 translocations are associated with progression from follicular lymphoma to the more aggressive diffuse large B cell lymphoma, and PAX5/IgH translocations have been identified in a subset of non-Hodgkin’s lymphomas." (PMID 29535729, 2018). "Initial histopathological examination of the resected lesion, due to aberrant expression of B-cell markers (PAX-5, CD79a, c-Myc, Bcl-2), led to a misdiagnosis of diffuse large B-cell lymphoma (DLBCL)." (PMID 41561755, 2025). "Furthermore, in the context of fine-needle aspiration cytology (FNAC), the utilization of specific markers such as CD15, CD30, and PAX5 has proven to be valuable for the identification of Hodgkin lymphoma (HL) and non-Hodgkin large B-cell lymphoma, specifically diffuse large B-cell lymphoma (DLBCL)." (PMID 37443818, 2023). "Research indicates that in cases of CD20-negative diffuse large B-cell lymphoma (DLBCL), the inclusion of CD79a and PAX5 in the immunohistochemical panel can significantly enhance diagnostic specificity and sensitivity." (PMID 40428800, 2025). "Diffuse large B‐cell lymphoma is the most common type of testicular lymphoma, typically expressing CD19, CD20, CD22, CD79a, and PAX5 markers." (PMID 40735721, 2025). "Diffuse large B‐cell lymphoma typically expresses pan‐B markers CD19, CD20, CD22, CD79a, CD45RA, PAX5 markers, and other markers CD10, BCL6, BCL2, MYC, and MUM‐1." (PMID 40735721, 2025). "Postoperative pathology revealed diffuse large B-cell lymphoma (DLBCL), with immunohistochemically related positive indicators, including CD20, CD79a, LCA, MUM-1, PAX5, C-MYC, BCL-2, and BCL-6, in all patients." (PMID 35734472, 2022). "Immunohistochemical staining on 35th day showed positive markers for CD20, EBER, BCL-2, PAX5, MUM-1 and a Ki-67 rate of 70%, which was consistent with a diagnosis of diffuse large B-cell lymphoma (DLBCL)." (PMID 31906982, 2020). "In the pathogenesis of Diffuse large B-cell lymphoma (DLBCL), BCL6 transcriptional repressor is the most frequently involved oncoprotein, which is required to sustain proliferation and survival of DLBCL cells through regulation of specific targets such as PRDM1, c-Myc or PAX-5." (PMID 30143009, 2018).
myeloma (20 papers, 2007 to 2024). "In agreement with the flow cytometric pattern described previously, less mature CD138+PAX5+ plasma cells were significantly more abundant in WM than in marginal zone lymphoma (MZL) or plasma cell myeloma (multiple myeloma or MM)." (PMID 36494694, 2022). "In multiple myeloma, a plasma cell disorder, diverse PAX5 isoforms have been identified accompanied with low levels of the WT PAX5 expression." (PMID 36387144, 2022). "This situation is highlighted by our findings for ASM index SNP rs4487645, which coincides with a GWAS peak for AL amyloidosis and multiple myeloma and disrupts an ENCODE PAX5 discovery motif (PAX5_disc3) that is significantly enriched among ASM loci." (PMID 32594908, 2020). "Overexpression of PAX5 induces apoptosis in multiple myeloma, whereas knockdown of PAX5 increases cell proliferation and cisplatin resistance in esophageal squamous cell carcinoma." (PMID 32260415, 2020). "DEPTOR knockdown in H929 and MM1S cell lines induced dedifferentiation of myeloma cells, as demonstrated by the upregulation of PAX5 and BCL6, the downregulation of IRF4, and a clear reduction in cell size and endoplasmic reticulum mass." (PMID 28420429, 2017). "In this study, 17-AAG, an HSP90 inhibitor candidate in human clinical trials (multiple myeloma; phase 3), potentially exerted an inhibitory activity on EZH2, PAX5 and KHDRBS1 genes associated with the risk of developing metastatic phenotypes by modulating gene expression." (PMID 38254687, 2024). "Furthermore, genetic susceptibility was indicated in ALL and multiple myeloma, with constitutional mutations in genes such as IKZF1, SH2B3, PAX5 (ALL) and KDM1A/LSD1 (multiple myeloma)." (PMID 36998465, 2023). "Since the PAX5 TF is a master regulator of B cell development, these ASM mapping data are post-GWAS evidence suggesting involvement of a relevant biological pathway in susceptibility to multiple myeloma, a B cell malignancy." (PMID 32594908, 2020). "Immunohistochemical staining was strongly positive for CD45, CD20 (most positive) and TdT (x40 objective); positive for paired box 5 (PAX5), CD19, CD79a, CD10, multiple myeloma 1; and negative for B‐cell lymphoma 2 (BCL2), BCL6, CD5, cyclin D1, CD1a, CD99, CD117, CD34, MPO and light chains." (PMID 36051009, 2022).
B-cell acute lymphoblastic leukemia (18 papers, 2015 to 2025). A neoplasm of lymphoblasts committed to the B-cell lineage, typically composed of small to medium-sized blast cells. "Alteration in PAX5 has been implicated in developing human B-cell malignancies, including precursor B-cell acute lymphoblastic leukemia." (PMID 39408690, 2024). "In B cell progenitors, lineage commitment is mediated by Pax5, which is commonly mutated in B cell acute lymphoblastic leukemia." (PMID 39424985, 2024). "Another important function of Pax5 is to suppress B cell tumorigenesis in mice and humans, where heterozygous PAX5 mutations prominently contribute to the development of B cell acute lymphoblastic leukemia." (PMID 35947077, 2022). "PAX5 is one of the most frequently mutated genes in B-cell acute lymphoblastic leukemia (B-ALL), and children with inherited preleukemic PAX5 mutations are at a higher risk of developing the disease." (PMID 33154497, 2020). "Deletion of ZNRF1 may be involved in the mechanism of B-cell acute lymphoblastic leukemia associated with PAX5 alteration." (PMID 31417866, 2019). "EBF1 functions as a transcription factor, which, in conjunction with PAX5, significantly regulates the developmental process of normal and malignant B-cell acute lymphoblastic leukemia by binding to MYC gene regulatory elements." (PMID 39794701, 2025). "B-cell acute lymphoblastic leukemia is genetically diverse, with one of the most commonly altered genes being PAX5." (PMID 38539499, 2024). "Human PAX5 also plays a key role in B cell acute lymphoblastic leukemia (B-ALL) as a haploinsufficient tumor suppressor gene as well as a partner gene of different oncogenic PAX5 translocations." (PMID 37725138, 2023). "PAX5, a master regulator of B cell development and maintenance, is one of the most common targets of genetic alterations in B-cell acute lymphoblastic leukemia (B-ALL)." (PMID 36387144, 2022). "We analyzed the function of PAX5::CBFA2T3 (PAX5‐C), a fusion protein found in B‐cell acute lymphoblastic leukemia." (PMID 40643079, 2025). "In B cell acute lymphoblastic leukemia (B-ALL), a number of PAX5 fusion proteins have been reported, including PAX5::ETV6, a fusion of the paired domain from PAX5 to a large portion of the ETV6 protein, which includes its helix-loop-helix and ETS domains." (PMID 38473380, 2024).
breast carcinoma (18 papers, 2012 to 2025). "Specifically, PAX5 is shown to regulate hallmark phenotypic transitioning programs known as the epithelial to mesenchymal transition (EMT) during breast cancer cell metastasis and disease progression." (PMID 36077495, 2022). "In order to draw specific correlations between Pax-5 expression patterns and patient sample physiognomies, we attempted to associate Pax-5 expression profiles to breast cancer pathology subtypes and estrogen receptor (ER) status." (PMID 28076843, 2017). "We also present an important role for Pax-5 in the phenotypic transitioning processes and aggressive features associated with breast cancer malignancy and disease progression." (PMID 28076843, 2017). "Interestingly, we also detected a decrease of Pax-5 expression (30%) suggesting the loss of Pax-5 expression during breast cancer EMT." (PMID 28076843, 2017). "To determine whether Pax-5-mediated suppression of breast cancer viability was caused by caspase-dependent apoptosis, we monitored caspases 3/7 activity in these cells over time." (PMID 28076843, 2017). "Notably, PAX5 is able to control the expression of non-coding-RNA, which could be equally associated with breast cancer progression." (PMID 40506992, 2025). "Immunohistochemical evaluation found constitutive expression of PAX5 in mammary epithelial cells, promoting gene expression of E-Cadherin, while in breast cancer it suppressed breast cancer cell migration, invasion, and promoting cell adhesion properties." (PMID 40506992, 2025). "In breast cancer, numerous studies have demonstrated that PAX5 plays an inhibitory role in the invasive capacity of malignant cells." (PMID 40506992, 2025). "The main mechanisms through which PAX5 is silenced in aggressive breast cancer concern the hypermethylation of its promoter." (PMID 40506992, 2025). "In biopsies derived from breast cancer patients, both PAX5 and miR-215 showed a reduced expression within the cancer lesions compared to adjacent normal tissue." (PMID 40506992, 2025). "PAX5 ability to reduce cells invasion in breast cancer cells has been proved also in MCF-7 and MDA-MB-231 cell lines." (PMID 40506992, 2025). "In breast cancer cell lines, PAX5 inversely correlates with pro-malignant FAK expression, thereby promoting the maintenance of epithelial cell characteristics." (PMID 40506992, 2025). "Besides, 236 cases of breast cancer patients (including 124 cases with PAX5 low expression and 112 cases with PAX5 high expression) were collected and analyzed, which results were consistent with the prediction that PAX5 over-expression was associated with worse prognosis." (PMID 37403081, 2023). "The expression of PAX5 was significantly down-regulated in breast cancer tissues, while the expression levels of DNMT1 and ZEB1 were both up-regulated in breast cancer tissues, compared with normal tissues." (PMID 37403081, 2023). "PAX5 is a nuclear transcription factor that involved in multiple biology process and cancer progression including breast cancer." (PMID 37403081, 2023). "In summary, we demonstrate the existence of PAX5-miR-142-5p/3p-DNMT1/ZEB1 feedback loop in regulation of breast cancer." (PMID 37403081, 2023). "Taken together, PAX5-miR-142-DNMT1/ZEB1 formed a feedback loop in regulation of breast cancer progression." (PMID 37403081, 2023). "In this study, we investigated the mechanism of miR-142-5p/3p in breast cancer progression and identified the PAX5 as the upstream regulator of miR-142." (PMID 37403081, 2023).
breast carcinoma (continued). "Studies demonstrate that PAX5 overexpression in breast cancer cells leads to a decrease in proliferation, colony formation, and migration through the induction of pro-epithelial features." (PMID 36077495, 2022). "As a result, the Pax-5 transcripts from breast cancer cells characterized by 3′UTRs 3.3 kb would theoretically escape more than half (51.5%) of the targeting miRNAs in comparison to the reported full-length 3′UTRs." (PMID 35011638, 2021). "The methylation rates in tissue DNA of patients with breast cancer were found between 33% and 58% for PAX5 gene and between 49% and 55% for TMPRSS2 gene according to ß-actin gene." (PMID 30792990, 2019). "In our study groups, we found that methylation rates of primary breast cancer tissues were 70% (7/10) for PAX5 and 60% (6/10) for TMPRSS2, respectively." (PMID 30792990, 2019). "In the patient group with breast cancer, PAX5 was found methylated in 7 out of 10 (70%) tumor tissues, only one sample (10%) was observed as methylated in 3D culture, and no methylation was observed in any 2D culture samples." (PMID 30792990, 2019). "We next set out to assess the ability of Pax-5 to modulate breast cancer cell adherence to fibronectin (FN), a component of ECM." (PMID 28076843, 2017). "Altogether, these results strongly suggest that Pax-5 mitigates aggressive cellular and molecular processes which are essential for breast cancer disease progression." (PMID 28076843, 2017). "We first made use of the aggressive mesenchymal-dominant MB231 breast cancer model to study cellular migration following Pax-5 transfection." (PMID 28076843, 2017). "Our findings suggest that Pax-5 promotes epithelial characteristics while concomitantly reducing mesenchymal features in breast cancer cells; a process reminiscent of MET." (PMID 28076843, 2017). "In the present study, we characterize Pax-5 expression profiles in breast cancer using mammary tissue-arrays and show that Pax-5 expression is prevalent in 97% of mammary samples tested." (PMID 28076843, 2017). "We found that the Pax-5/CD19 mRNA expression ratios were up to 3 fold higher in breast cancer tissues in comparison to tonsil tissues." (PMID 28076843, 2017). "More importantly, we show that Pax-5 is a potent inducer of pro-epithelialisation regulator E-cadherin which leads to breast cancer MET." (PMID 28076843, 2017). "Recent studies have presented opposing findings pertaining to the putative expression of the Pax-5 gene in breast carcinoma." (PMID 28076843, 2017). "The seemingly conflicting functions exhibited by Pax-5 on breast cancer malignancy and progression appear to be highly dependent on particular cellular contexts during the metastatic cascade." (PMID 28076843, 2017). "More precisely, Pax-5 suppressed breast cancer cell migration, invasion and tumor spheroid formation while concomitantly promoting cell adhesion properties." (PMID 28076843, 2017). "We also demonstrate that Pax-5 suppresses cellular anchorage-independent growth, migration and invasion; processes all involved in breast cancer malignancy." (PMID 28076843, 2017). "In this study, we provide evidence for the Pax-5 gene to regulate breast cancer cell phenotype identity and EMT-MET processes." (PMID 28076843, 2017). "The prevalence of Pax-5 expression in mammary tissues in addition to its involvement in malignant and phenotypic transitioning processes, presents Pax-5 as a potential biomarker for breast cancer tissues." (PMID 28076843, 2017). "To further elucidate Pax-5 function in breast cancer processes, we performed various embedded culture condition to assess other breast cancer processes." (PMID 28076843, 2017). "More interestingly, we found that in contrast to its oncogenic effects in lymphoid-derived cancers, Pax-5 confers a tumor suppressor role in breast carcinoma." (PMID 28076843, 2017).